IL2 (interleukin 2)
Diseases named in the same sentence as IL2 in open-access papers (continued):
Sharing a sentence is not in itself a finding about the gene and the disease.
melanoma (continued). "Our findings provide preliminary evidence for a volume-outcome relationship for RCC and melanoma patients undergoing HD IL2 treatment." (PMID 26799322, 2016). "As in some cases, we have observed similar STAT signaling response from melanoma patients in comparison to healthy donors but yet progress from the disease after HD IL-2 therapy." (PMID 27153543, 2016). "It has been reported that complexes composed of interleukin (IL)-2 and stimulating anti-IL-2 antibody (IL-2C) suppress malignant melanoma growth." (PMID 26772545, 2016). "High dose (HD) IL-2 therapy has been used as an effective immunotherapy against melanoma for about 20 years." (PMID 27153543, 2016). "Our study has important implications for RCC and melanoma patients who are considering HD IL2 treatment and physicians who are referring their patients for HD IL2 therapy at specialty centers." (PMID 26799322, 2016). "From 2003 to 2011, the NIS contained 29,532 patients (weighted number) with RCC (weighted N = 8,969) or melanoma (weighted N = 20,563) who received HD IL2." (PMID 26799322, 2016). "Multivariate predictors of in-hospital mortality in melanoma and renal cell carcinoma patients receiving high dose interleukin-2 (weighted N = 29,184)." (PMID 26799322, 2016). "Initial studies in the 1980s demonstrated the ability of interleukin-2 (IL-2) to mediate tumor regression in melanoma and other malignancies." (PMID 26850630, 2016). "In this retrospective analysis HD IL-2 therapy displayed antitumor activity in melanoma patients who progressed following treatment with ipilimumab." (PMID 27660706, 2016). "Immunotherapy using interleukin-2 (IL-2) has long been a part of our historically small armamentarium against advanced melanoma." (PMID 27826593, 2016). "The notion that T cells are primed and ready to fight tumors, but are limited by the tumor microenvironment has been demonstrated in patients with melanoma in which lymphocytes from excised tumor masses will expand when supplemented with IL-2." (PMID 27007050, 2016). "Different immunotherapeutic approaches, including IL-2 therapy, and adoptive T cell transfer achieved promising results with a substantial clinical benefit at least in a fraction of melanoma patients." (PMID 27563819, 2016). "A recent study reported that both tyrosine phosphorylation of signal transducer and activator of transcription 5 (STAT5) and STAT1 in response to IL-2 stimulation were impaired in melanoma patients and this was correlated with increasing clinical stage." (PMID 27153543, 2016). "In this study we queried the PROCLAIM database for patients with advanced malignant melanoma who had received HD IL-2 following treatment with ipilimumab and compared them to patients who had not received prior immune checkpoint blockade." (PMID 27660706, 2016). "Allogeneic IL‐2 activated human NK cells from healthy donors were used as effectors against either the BRAFi‐resistant, and the respective parental, BRAFi‐sensitive melanoma cell line." (PMID 26564811, 2016). "For example, Kanimura and colleagues have trialed IL-2/anti-IL-2 complex treatment in a mouse model of B16 melanoma, and Tomala and colleagues in a mouse model of BCL1 leukemia as cancer immunotherapy." (PMID 27391012, 2016). "IL-2 has been used as monotherapy and in combination with chemotherapy or biologics for the treatment of cancer with significant clinical benefit for melanoma and renal cell carcinoma patients." (PMID 27049955, 2016). "We conclude that α-CD137 and α-PD-1 antibodies were most effective in enhancing SBRT-induced tumor growth delay in this mouse melanoma model, outperforming the ability of IL-2, or the combination of α-CTLA-4 and α-PD-1 to synergize with SBRT." (PMID 27160390, 2016). "In an in vivo model of human melanoma, administration of high dose IL-2 (HDIL-2) led to expansion of both the Th17 and regulatory T cell compartments, demonstrating increased cell counts and frequencies early in the course of treatment." (PMID 27413254, 2016).
melanoma (continued). "Chemotherapy agents such as temozolomide, dacarbazine, high-dose IL-2, paclitaxel and carboplatin are commonly used in the treatment of melanoma." (PMID 27845904, 2016). "We also observed an inverse correlation of the proportion of pSTAT5+CD56lo NK cells with aging in the melanoma patients in response to IL-2 with age, whereas the proportion of pSTAT5 expressing CD4+ T cells was positively associated with aging." (PMID 27153543, 2016). "We found that melanoma patients exhibited significantly lower IL-2-induced pSTAT1 level than healthy controls in T and NK cell subsets." (PMID 27153543, 2016). "Immunotherapy using high dose interleukin-2 (HD IL2) in patients with renal cell carcinoma (RCC) and melanoma is associated with severe toxicities." (PMID 26799322, 2016). "Two later reports of patients with melanoma also describe the objective response of intracranial metastases to immunotherapy (HD IL-2 and adoptive cell therapy), confirming the ability of immunotherapy to induce regressions of intracranial tumors." (PMID 27891227, 2016). "Despite these limitations, our study represents the largest sample of patients, who have received HD IL2 for melanoma or RCC." (PMID 26799322, 2016). "From 2003 to 2011, 29,532 patients with RCC or melanoma who received HD IL2 were identified, and 124 died during the hospitalization (0.4%)." (PMID 26799322, 2016). "Other therapies for melanomas with distal metastasis currently include high-dose IL-2 therapy and molecular targeted drugs." (PMID 25763309, 2015). "These T cells were also able to cure melanoma metastases as effectively as, and sometimes better than, T cells grown in IL-2." (PMID 25903148, 2015). "A recent study analyzed the adoptive transfer of mismatched lymphocytes activated in vitro with recombinant human IL-2 (NCT00855452) for the induction of graft-versus-tumor effect in metastatic solid tumors including melanoma." (PMID 26779186, 2015). "The combined therapy using nonmyeloablative chemotherapy, T cell infusion, and systemic IL-2 has demonstrated 20% complete response rate and 70% overall response rate in melanoma patients." (PMID 26090481, 2015). "Low-dose IL-2, in combination with IL-21, induced anti-tumor immunity and long-term curative effects in a murine melanoma model." (PMID 26529512, 2015). "Melanoma patients treated with high-dose IL-2 have shown an expansion of the Treg compartments; however, those patients with a clinical response exhibit a paradoxical decrease in Tregs following treatment." (PMID 25992289, 2015). "Others compared the efficacy of the IL-2/anti-IL-2 mAb complex with IL-2 treatment alone in a B16 melanoma mouse model." (PMID 26220086, 2015). "Melanoma-derived PAEP significantly inhibited the PHA-stimulated secretion of both IL-2 (decreased by 17.1%, p<0.05) and IFN-γ (decreased by 61.7%, p<0.05) from Th1 cells, but did not affect those secretions of Th1-free T helper cells." (PMID 25785839, 2015). "Although IL-2 has only been recommended for the treatments of melanoma and renal cancer, it has been combined with other agents to treat a spectrum of other cancers, including ovarian, breast, gastric, lung, colorectal, and head-and-neck cancers." (PMID 26495849, 2015). "Recently, we have identified in metastatic LN a new subset of mature CD56brightCD16+ NK cells that display cytotoxic activities against melanoma cells following IL-2 or IL-15 stimulation." (PMID 26218530, 2015). "Considering the success of imiquimod cream for treating melanoma and the latest results of IL-2 therapy in diabetic patients, it is realistic to develop topical immunotherapy." (PMID 26276522, 2015). "The use of high-dose IL-2 in renal cell carcinoma and melanoma are two rare instances in oncology where an effective treatment has been identified to potentially cure a widely metastatic solid tumor." (PMID 26557408, 2015). "A clinical trial has been proposed to assess the use of intravenous AA as an adjuvant to IL-2 treatment of melanoma." (PMID 26547841, 2015).
melanoma (continued). "The results indicated that Melanoma-derived PAEP significantly inhibited the secretion of both IL-2 and IFN-γ from Th1 cells." (PMID 25785839, 2015). "This combination immunotherapy did improve therapeutic responses over either CTLA-4 blockade or IL-2 monotherapy against the poorly immunogenic B16 melanoma." (PMID 25992289, 2015). "IL-2 has shown promise for the treatment of a number of cancer types (melanoma, renal cell carcinoma, hepatocellular carcinoma, mesothelioma, ovarian cancer, gastrointestinal cancer, lung cancer, and basal cell carcinoma)." (PMID 26529512, 2015). "Clinically, IL-2 has been used for immunotherapy of several kinds of cancers, such as melanoma and renal cell carcinoma." (PMID 26529512, 2015). "Interleukin-2 (IL-2) therapy has been used with success in curing meta­static renal cell carcinoma and melanoma in a small minority of patients." (PMID 26557408, 2015). "Compared with other treatments, high-dose IL-2 has consistently delivered durable complete responses of 10% to 15% in melanoma patients and 15% to 25% of patients with renal cell carcinoma." (PMID 26557408, 2015). "We sought to examine the impact of baseline measurable markers of immune status on survival in stage IV melanoma patients treated aggressively at a high-dose IL-2 center during the time period of 2010 and later." (PMID 25932372, 2015). "IL-2 is FDA approved for the treatment of metastatic renal cell carcinoma and melanoma, and responses to IL-2 have been reported in several other cancers including lung and breast cancers." (PMID 26301204, 2015). "Intriguingly, in an independent study, NRAS status was suggested as a new candidate biomarker for selecting melanoma patients for high-dose interleukin-2 treatment (HD IL-2)." (PMID 26305188, 2015). "In melanoma, for instance, interleukin-2 (IL-2) and interferon (IFN)-α have become standard therapies as adjuvants to chemotherapy to enhance immune response in treating metastatic disease." (PMID 24804271, 2014). "High-dose IL-2 has been available to treat patients with melanoma and renal cancer since the 1990’s." (PMID 24855563, 2014). "A registry is an important resource in helping establish best practices for IL-2 therapy as new agents are improved for the treatment of melanoma and renal cell carcinoma." (PMID 25031835, 2014). "Melanoma has been a particular target of immunotherapy because of its inherent immunogenicity, and early therapeutic approaches such as interleukin-2 (IL-2) and interferon-alpha2b (IFNα2b) aimed to stimulate these antitumor immune responses." (PMID 25389405, 2014). "PROCLAIM establishes a clinical database on patients diagnosed with advanced kidney cancer (mRCC) and melanoma (mM) who are treated with HD IL-2." (PMID 25031835, 2014). "For patients who went on to receive systemic medical therapy after IL-2, the median survival from start of IL-2 therapy was 18.4 months in patients with melanoma and 27.0 months in RCC." (PMID 24855563, 2014). "Prospective clinical trials have reported a response rate of around 16% for melanoma patients treated with IL-2." (PMID 25245327, 2014). "A retrospective analysis of the outcomes of 500 patients with metastatic renal cell carcinoma (RCC) (n = 186) or melanoma (n = 314) treated with high-dose IL-2 between 1997 and 2012 at Providence Cancer Center was performed." (PMID 24855563, 2014). "Interferon, interleukin-2 and other biological response modifiers for malignant melanoma have a moderate effect." (PMID 24959253, 2014). "There is one previous study with findings similar to ours showing a favorable correlation with response and IL-2-induced hypotension in melanoma patients." (PMID 24855563, 2014). "Early studies of IL-2 demonstrated impressive results in a subset of melanoma and renal cell cancer patients." (PMID 24884532, 2014).
melanoma (continued). "High-dose of interleukin-2 (IL-2) increases relapse-free survival, but a low response rate and significant toxicities precludes its applications in many cases of melanoma." (PMID 25521755, 2014). "The present paper includes the last analysis of our study conducted in a cohort of patients treated either with IL-2 or adoptive T-cell therapy (TILs + IL-2) as adjuvant treatment in stage III melanoma patients." (PMID 24741578, 2014). "The proportion achieving a complete or partial response was greater in patients with melanoma who received 5 or more compared with 4 or fewer IL-2 cycles (p < 0.0001)." (PMID 24855563, 2014). "A major difference between the HD bolus IL-2 regimen and other chemotherapeutic melanoma therapies lies in the duration and quality of the responses obtained." (PMID 25245327, 2014). "A study performed in melanoma using the same adenoviral vector with interleukin-2 instead of interferon-γ showed regression of metastatic melanoma lesions in 6 out of 21 patients treated at the same dose of 3.10 viral particles (vp) by injection." (PMID 24586226, 2014). "Overall, our findings document that γδT cells in PBMC from melanoma patients responded well to zoledronate plus IL-2/IL-15." (PMID 25101086, 2014). "The first immunotherapy to be approved by the Food and Drug Administration (FDA) for treatment of advanced melanoma was interleukin-2 (IL-2) but, like dacarbazine, response rates were low even at high-doses of treatment." (PMID 24899250, 2014). "Rosenberg's group first described the adoptive cell transfer-based immunotherapy in humans in 1988 using bulk cultures of lymphocytes derived from autologous melanoma tumors, infused together with high doses of IL-2 in metastatic melanoma patients." (PMID 24741578, 2014). "Interleukin-2 (IL-2) therapy has been demonstrated to induce responses in 10-20% of advanced melanoma and renal cell carcinoma patients, which translates into durable remissions in up to half of the responsers." (PMID 24884532, 2014). "IL-15 alone or in combination with IL-2 has been used successfully in cultures of tumor-infiltrating αβT cells isolated from melanoma and Merkel cell carcinoma patients." (PMID 25101086, 2014). "Large doses of IL-2 have been suggested by the National Comprehensive Cancer Network as the treatment of choice for advanced melanoma." (PMID 25430016, 2014). "Most notably, vaccination with the gp100-209:217(210M), an HLA-A*0201-restricted epitope derived from the melanoma antigen gp100, significantly improved the clinical response and median overall survival of stage IV melanoma patients receiving IL-2 therapy." (PMID 24690990, 2014). "He received two more cycles of IL-2, but his melanoma subsequently progressed and he began treatment with ipilimumab in November 2011." (PMID 25317333, 2014). "The median survival of patients who enrolled in palliative care or hospice or who declined further medical therapy after IL-2 (due to disease progression) was 3.3 and 2.4 months for patients with melanoma and RCC, respectively." (PMID 24855563, 2014). "Activation was achieved by in vivo and in vitro exposures to the melanoma tumor cell line B16 that was followed by differentiation in IL-2." (PMID 25101668, 2014). "The tumor response and survival reported here after IL-2 are superior to the published literature and confirms that durable regressions of disease are achievable in patients with advanced melanoma and renal cancer." (PMID 24855563, 2014). "The median time to starting a new treatment after IL-2 was 3 and 5.1 months for melanoma and renal cancer, respectively." (PMID 24855563, 2014). "In melanoma patients, tumor peptide antigen vaccination combined with low-dose cyclophosphamide and low-dose IL-2 evoked Th1-like Treg accumulation, in line with a less tolerogenic microenvironment and with enhanced IL-12 availability." (PMID 23986759, 2013).
melanoma (continued). "The first immunotherapy to be approved by the Food and Drug Administration (FDA) for treatment of advanced melanoma was interleukin-2 (IL-2) but, like dacarbazine, response rates are low." (PMID 23738073, 2013). "For examples, resveratrol prevents injury of endothelial cells in high-dose interleukin-2 therapy against melanoma." (PMID 23762150, 2013). "IL-2 activated NK cells from patients efficiently lysed melanoma cells and displayed higher inter-individual variability than donors." (PMID 24204708, 2013). "We show that IL-2 activated NK cells from patients efficiently lyse melanoma cells independently to their clinical stage." (PMID 24204708, 2013). "A recent study found that levels of peripheral Tregs were negatively correlated with the clinical response to adoptive immunotherapy in melanoma patients, and Treg reconstitution depended on the number of IL-2 doses that were administered." (PMID 23589107, 2013). "Patients with melanoma brain metastases are usually considered to be ineligible for HD IL-2 therapy due to concerns of life-threatening cerebral edema and neurotoxicity." (PMID 23762555, 2013). "Blood NK cells from 9 patients (stage II to IV) and 6 donors were immunoselected and activated by IL-2 for 6 days before measuring their capacity to lyse melanoma cells." (PMID 24204708, 2013). "Injecting SAN melanoma cells into the tail vein of IL2-NOD-SCID mice produced prominent multifocal lesions in lungs and liver after 28 days." (PMID 23559012, 2013). "T-cell-mediated antitumor therapies, such as IL-2, have played an important role in progressing immunotherapeutic approaches to the treatment of advanced melanoma." (PMID 23738073, 2013). "Our aim was to describe our institution's experience of HD IL-2 therapy in melanoma patients with brain metastases." (PMID 23762555, 2013). "In mixed lymphocyte reactions with T cells, DCs, and melanoma cells, T cells produced larger amounts of IL-2 when CD200 in melanoma cells was knocked down with shRNA specifically targeting the CD200 ligand." (PMID 24194739, 2013). "Using a dynamic label-free assay, we found that immunoselected IL-2 activated blood NK cells from patients efficiently lysed melanoma cells through NKp46 and NKG2D receptors, independently to the clinical stage." (PMID 24204708, 2013). "Until the response of other treatments can be further clarified, HD IL-2 should be considered as a treatment option in patients with melanoma brain metastases who are otherwise eligible for therapy." (PMID 23762555, 2013). "All previous reports have described patients who had received HD IL-2 with untreated melanoma brain metastases, except for one case in which the patient completed whole brain radiation prior to HD IL-2 treatment." (PMID 23762555, 2013). "All cultures displayed enhanced killing activity of melanoma cells when compared to overnight incubation with IL-2 (d1), as well as in the mismatched setting, as compared to the matched setting." (PMID 23483943, 2013). "For the majority of patients, both the survival after diagnosis of melanoma brain metastasis and survival after HD IL-2 initiation were longer when compared to the predicted median duration of survival based on the patient's DS-GPA score." (PMID 23762555, 2013). "We think that HD IL-2 should be considered as a treatment option in patients with melanoma brain metastases who are otherwise eligible for therapy." (PMID 23762555, 2013). "Preclinical studies have shown antitumor effects of IT injections of IL2, leading to clinical testing of IT injections of IL2, especially in melanoma." (PMID 24634778, 2012). "How the tolerance inducing capacity of IL-2 can be reconciled with the anti-tumor effects in 15–25% of patients with mRCC and melanoma remains elusive." (PMID 23118856, 2012). "In a separate study, we evaluated the mechanism of action of systemic IL-2 administration by sampling melanoma metastases before and during treatment." (PMID 22576055, 2012).